LEP (leptin)
Diseases named in the same sentence as LEP in open-access papers (continued):
Sharing a sentence is not in itself a finding about the gene and the disease.
Obesity (continued). "IL-6 produced during exercise may alter leptin in the ARC, affecting post-exercise eating behavior IL-18 knockdown mice cause hyperphagia, obesity, and insulin resistance." (PMID 39691381, 2024). "Subsequent investigations focused on the role of leptin in SF-1 neurons and obesity." (PMID 39479520, 2024). "The ob/ob mouse model, generated in 1949, is the most popular model for severe hyperglycemia and a monogenic model of obesity caused by a lack of leptin production." (PMID 38339160, 2024). "Obesity was associated with higher serum levels of EGF, Groα, MCP1, MIP-1b, MDC, VEGFα, and Leptin." (PMID 38541912, 2024). "The mechanism by which OS promotes obesity through leptin is complex." (PMID 39000383, 2024). "Type 2 diabetes in males of this strain results from polygenic interactions producing a moderate obesity rather than the massive obesity elicited by mutations in the leptin or leptin receptor axis, such as ob/ob or db/db mice." (PMID 38444587, 2024). "Serum leptin levels are usually increased and severe obesity is prominent in these patients." (PMID 38397265, 2024). "However, leptin also possesses potent pro-inflammatory properties, which become particularly impactful in the context of obesity." (PMID 39064298, 2024). "Leptin resistance develops when receptors for leptin signaling are compromised in obesity." (PMID 38840158, 2024). "This innovative research broadens our understanding of how leptin is regulated and provides a novel mechanism that could be targeted to treat obesity." (PMID 39872508, 2024). "However, in the separate analysis of the OW/OB group, we found that obesity influences the leptin concentration greater than overweight." (PMID 38668349, 2024). "Nevertheless, the relationship between leptin, obesity, and CRC is not fully understood." (PMID 39621160, 2024). "Substantial evidence has been presented in the literature that leptin functions as a cardiac hypertrophic factor and thus can contribute to heart disease, particularly heart failure, under conditions of hyperleptinemia such as that seen in obesity." (PMID 38256208, 2024). "The authors speculate that leptin might have a post-prandial regulatory role, possibly in fat oxidation in skeletal muscle, that is disrupted in individuals with obesity." (PMID 39771019, 2024). "This metabolic and inflammatory damage may arise from either resistance to leptin action in specific tissues or an excess of leptin action attributed to obesity-related hyperleptinemia." (PMID 38397015, 2024). "This methylation difference in the LEP gene was related to breast milk’s effect on obesity; however, they stated that more studies are needed in future to determine whether it can be considered a protective effect." (PMID 39594868, 2024). "In obesity-related hypogonadism, excess body fat and elevated levels of leptin play crucial roles." (PMID 38892561, 2024). "Treatment of T2D patients using leptin replacement has been reported to improve their metabolic disorder status, to reduce insulin insensitivity and reverses obesity, suggesting that leptin dysfunction may also directly affect glucose metabolism." (PMID 38974903, 2024). "This may indicate that while leptin dysregulation is common in obesity, its role as a differentiator for MetS may be limited in the study group." (PMID 39771030, 2024). "In this study, we recruited a Chinese family with very low serum leptin concentrations and obesity." (PMID 39041042, 2024). "Therefore, understanding the intricate relationship between obesity, leptin, and thyroid function is essential for comprehensive management strategies and targeted interventions to improve metabolic health in women with obesity." (PMID 38892561, 2024). "As we noticed, most of the anti-obesity gene therapy approaches exploit the possibility of inducing white-to-beige adipose transition by overexpressing the genes coding for secreted factors, such as leptin, FGF21, or BMP7." (PMID 38931457, 2024).
Obesity (continued). "Moreover, our data revealed significantly elevated plasma leptin levels in the obesity cohort and a significant positive correlation with the BMI values." (PMID 38172514, 2024). "A study in female transgenic skinny mice overexpressing leptin suggested that chronic hyperleptinemia, as found in obesity, may downregulate leptin signaling in the hypothalamus, resulting in decreased hypothalamic function." (PMID 38353886, 2024). "Understanding this dynamic interaction might provide deeper insights into how leptin signaling and cellular responses are modulated, particularly in the context of metabolic disorders such as obesity." (PMID 39916981, 2024). "Leptin is greatly upregulated, and adiponectin is downregulated during obesity." (PMID 39596205, 2024). "It is very important to highlight that the absence of a positive response to the interventions in this study, in the variables related to obesity, may be related to the fa/fa animal model, which has a genetic alteration that promotes leptin resistance." (PMID 36702820, 2023). "Body weight loss improves insulin resistance and growth hormone secretion in obesity, which may be regulated by leptin according to preclinical studies." (PMID 36959287, 2023). "While obesity leads to imbalances in the circulating levels of peptides such as leptin, insulin, and ghrelin which can decrease or increase olfactory sensitivity, a compromised sense of smell can instead affect body weight by acting on the control mechanisms of eating behavior." (PMID 36837824, 2023). "These cells play a key role in the control of food intake and energy balance, and the disruption of this circuit by changes in leptin sensitivity or mutations in the genes encoding leptin, the leptin receptor, POMC, or MC4R, amongst other genes in this system, can lead to severe obesity." (PMID 36674935, 2023). "The mechanism of leptin resistance appears to be a vicious cycle: in states of obesity and hyperleptinemia, impaired leptin-mediated effects in turn promote further weight gain and prevent an efficient therapeutic use of exogenously supplied leptin, which is unable to exert its anorexic effects." (PMID 37239098, 2023). "Increased adiposity and metabolic dysfunction cause alteration of the gonadal axis through mechanisms mainly mediated by insulin resistance, adipokines, leptin and estrogens, which are elevated in men with overweight/obesity due to increased aromatization of T in the adipose tissue." (PMID 36282472, 2023). "Metformin is also shown to enhance leptin sensitivity and correct leptin resistance in high-fat-fed obese rats, and a combination therapy including metformin and leptin is helpful in the treatment of obesity." (PMID 37869164, 2023). "Unlike a more generally used model of diet-induced obesity, here, we employ a genetic model of obesity in which leptin signaling is curtailed causing hyperphagia and greater caloric intake." (PMID 37238651, 2023). "In addition to body mass index (BMI) and leptin as measures of obesity and adiposity, we metabolically phenotyped women by their fasting glucose, C-peptide and insulin sensitivity (ISHOMA index)." (PMID 37029207, 2023). "Increased leptin resistance due to dietary fat intake affects obesity." (PMID 36835164, 2023). "Obesity can be characterized as polygenic or ‘common obesity’ in 95% of cases, involving multiple genes that control thermogenesis, energy homeostasis, neurohormonal signalling and leptin-insulin interactions." (PMID 37233716, 2023). "Compared to MALFD, leptin is more robust in the effect of obesity, while adiponectin could interfere with the presentation of NAFLD regardless of HOMA-IR and adiposity." (PMID 36790383, 2023). "Further, an overstimulation of the endocannabinoid system in dietary fat-induced obesity may also contribute to diminished leptin response in POMC neurons." (PMID 37571301, 2023).
Obesity (continued). "Obesity increases the concentration of leptin and resistin in the serum of pregnant women, which hypothetically may be caused by the increased volume of adipose tissue." (PMID 37432262, 2023). "Consistently, reduced leptin levels were observed in the SKO-001-treated groups in our study, which may be linked to the anti-obesity effects of SKO-001." (PMID 36729332, 2023). "However, leptin is usually found in a higher concentration in individuals with obesity, a state described as hyperleptinemia." (PMID 38063544, 2023). "The Insufficiency leads to the development of leptin resistance, leading to obesity." (PMID 36852336, 2023). "So, lifestyle modifications such as diet change, exercise, and therapeutic interventions such as adiponectin and leptin supplementation may protect against obesity and, thus, obesity-induced memory loss." (PMID 37363537, 2023). "It has been suggested that leptin could be involved in the etiology of several effects commonly observed in patients with COVID-19 and obesity." (PMID 37240656, 2023). "As for the canonical pathway analysis results, several pathways associated with a comparison between the hypothalamus of fasted and fed mice were identified: triacylglycerol degradation, gustation pathway, leptin signaling in obesity, ketogenesis, and mevalonate pathway I." (PMID 36834616, 2023). "However, leptin resistance and hyperleptinemia in obesity promote hunger, increase food consumption, and induce inflammation." (PMID 38004453, 2023). "Leptin resistance occurs in obesity, due to chronic activation of JAK‐STAT signalling." (PMID 37275420, 2023). "High levels of leptin have been shown to increase oxidative stress in endothelial cells, favour VSMC migration and proliferation, decrease arterial distensibility, and contribute to obesity-associated hypertension." (PMID 36853380, 2023). "In a state of chronically increased leptin blood concentration among people with obesity, certain tissues may develop leptin resistance, which can contribute to fat accumulation in the liver." (PMID 37047363, 2023). "The impact of the leptin-mediated pathways may be compromised in obesity, as leptin resistance can contribute to the development of obesity hypoventilation syndrome and central sleep apnea." (PMID 36884287, 2023). "The NZBWF1 mouse is obese and has elevated leptin levels, in addition to developing hypertension and renal injury as the disease progresses, thus making it a clinically relevant model of hypertension and obesity in the setting of autoimmune disease." (PMID 38031726, 2023). "However, current research efforts focus on various combination therapies of leptin with leptin sensitizers to overcome states of leptin resistance in obesity and to improve the metabolic state." (PMID 37239098, 2023). "A recent cohort study found a negative association between hypomethylation of the LEP gene promoter, obesity, lipid profile modification, and low insulin sensitivity." (PMID 37375898, 2023). "This study examined the effects of maternal obesity on human colostrum lymphocytes and the intracellular mechanisms of lymphocyte modulation in the presence of leptin, adiponectin, and melatonin via cell proliferation; the release of intracellular calcium; and apoptosis induction." (PMID 36768983, 2023). "However, in the obesity group, in the presence of adiponectin and adiponectin + leptin, there was a decrease in the release of calcium from colostrum cells when compared to the same group treated with medium 199 (p < 0.05)." (PMID 36768983, 2023). "Both obesity and asthma have shown disturbed levels of leptin, adiponectin, resistin and visfatin." (PMID 36767041, 2023). "Notably, excessive food consumption increases leptin levels, a molecule responsible for obesity, which increases the frequency of TC." (PMID 37763777, 2023). "Leptin is a primary contributor to numerous cardiovascular risks connected to obesity." (PMID 37749096, 2023).
Obesity (continued). "Chronic HFD feeding leads to increased obesity and elevated circulating leptin levels, and ultimately to ‘leptin resistance’, both centrally and locally, which may be related to cardiovascular consequences." (PMID 38132854, 2023). "A meta-analysis has shown that obesity can alter serum levels of pro-inflammatory mediators (i.e., IL-6, CRP, TNF-a, resistin and leptin) in patients with periodontitis, while periodontitis can alter the levels of these mediators in patients with obesity, aggravating the inflammatory profile." (PMID 37798684, 2023). "In horses, serum leptin concentrations were positively correlated with obesity." (PMID 37628596, 2023). "A direct effect of leptin on skeletal muscle may contribute to the development of obesity and insulin resistance." (PMID 38001815, 2023). "Key hormones, such as insulin, leptin, ghrelin, and cortisol, as well as orexins, hypocretins, and melatonin, are believed to play a crucial role in the complex relationship between sleep and obesity." (PMID 38004130, 2023). "In obesity patients and in patients with MetS, the phenomenon of leptin resistance takes place." (PMID 37109160, 2023). "Therefore, obesity must be only one factor of a more complex multifactorial process involving the metabolism of leptin, growth hormone, insulin, hypertension, and with Homeostatic Model Assessment (HOMA), triglycerides and VLDL as additional elements." (PMID 37238326, 2023). "Perturbation of leptin and ghrelin levels may be related to increased appetite and calorie intake, which could lead to the development of obesity and diabetes, ultimately increasing mortality." (PMID 36892074, 2023). "Research suggests that patients with high BMI levels may experience reduced efficacy of benralizumab due to systemic inflammation caused by elevated levels of obesity-related cytokines like TNF-α, IL-6, and leptin." (PMID 38053108, 2023). "Deletion of STAT in POMC neurons, which have a response element to this factor in their promoter, does not completely abolish leptin effects and causes only mild obesity." (PMID 36674935, 2023). "Furthermore, this receptor mediates leptin resensitisation after the administration of celastrol, a potent anti-obesity agent, with the physical interaction between ObRb and IL-1R1 being the molecular mechanism involved." (PMID 36674935, 2023). "Besides adiponectin, leptin, the hormone responsible for food intake regulation, also plays an important role in obesity." (PMID 37998747, 2023). "With obesity, the direct action of leptin on PVN TRH presympathetic neurons that project to the RVLM may also contribute to hypertension, since knockdown of hypothalamic preproTRH normalized blood pressure in hypertensive diet-induced obese rats." (PMID 36769012, 2023). "Upon suppression/inhibition of the FAAH or MAGL enzymes, endocannabinoid levels are elevated, and hyperphagia, leptin resistance, and obesity may develop." (PMID 36830844, 2023). "Moreover, insulin-like growth factor- (IGF-) 1 and adipokines like leptin have been known to be involved in the context of obesity." (PMID 37082379, 2023). "Therefore, a deeper understanding of leptin regulation and action is necessary to develop leptin-based therapeutics against obesity." (PMID 37547309, 2023). "Increased levels of leptin and adiponectin are correlated with obesity." (PMID 36678304, 2023). "Furthermore, leptin induces sympathetic overactivity, particularly in people with obesity, which results in enhanced energy expenditure due to elevated epinephrine release at high estradiol levels." (PMID 36797524, 2023). "Also in that manuscript, mice with a mutation in the leptin gene (ob/ob) resulting in biologically inactive leptin, were used to analyze myeloma development in a genetic model of obesity." (PMID 36909335, 2023). "Leptin levels as well as the expression of adiponectin are significantly modified in obesity." (PMID 37446161, 2023).
Obesity (continued). "Indeed, plasma levels of leptin are elevated in individuals with obesity, although development of obesity is probably due to defective leptin transport to the central nervous system or due to leptin resistance." (PMID 36073672, 2023). "We hypothesized that attenuation of maternal obesity and serum leptin in pregnant BPH/5 mice will improve fetoplacental development by decreasing hypoxia markers and leptin expression at the maternal-fetal interface." (PMID 37829603, 2023). "Based on the results of the in vitro experiments and our earlier data on the pharmacodynamics of compound PI4, we studied the anorexigenic effect of compounds 1–4 and their influence on glucose homeostasis, as well as insulin and leptin resistance, in rats with diet-induced obesity." (PMID 36901928, 2023). "The stimulation of the HPT axis observed in obesity is mainly due to the centrally acting leptin, which regulates the activity of neurons in the hypothalamus and has both direct and indirect effects on thyrotropin-releasing hormone–stimulating thyroid hormone (TRH-TSH) secretion." (PMID 37374075, 2023). "Furthermore, Bbs2-, Bbs4-, and Bbs6-null mice exhibit high circulating leptin levels at an early age and before the development of obesity." (PMID 37571382, 2023). "In ob/ob mice, a spontaneous mutation in the leptin gene causes a lack of leptin in white adipose tissue, resulting in hyperphagic behavior, obesity, and inactivity." (PMID 37047048, 2023). "Central responsiveness to body-weight-reducing mediators, e.g., to leptin, changes during aging in a way, which may promote middle-aged obesity and aging cachexia." (PMID 37240340, 2023). "Serum leptin levels are elevated in obese individuals and it may be one of the factors linking obesity and psoriasis." (PMID 37275420, 2023). "(S) Diagram showing a leptin regulated GABAergic neural circuit reverses obesity." (PMID 37043384, 2023). "Suggesting a relationship between obesity and leptin secretion, another study demonstrated that abnormal leptin secretion could directly act on mesenchymal stem cells to down-regulate bone formation and promote bone marrow adipogenesis." (PMID 37330595, 2023). "Future studies are required to further understand the effects of G. pentaphyllum supplementation on skeletal muscle and exercise performance, along with leptin and adiponectin level, in healthy trained individuals as well as individuals with obesity and diabetes." (PMID 38004115, 2023). "Leptin is important in energy balance and appetite control and positively correlated with adipose tissues and nutritional status, and more recently has been extensively studied as a potential mediator of obesity-related cancer." (PMID 37371861, 2023). "However, obesity-related peripheral tissue resistance to leptin makes the hormone unable to exert its beneficial metabolic and cardiovascular effects." (PMID 36979669, 2023). "Among individuals with obesity, the expression of leptin is altered, leading to increased leptin concentrations—and leptin resistance—and impaired binding to leptin receptors (binding leptin to its receptors inhibits food intake and increases energy expenditure)." (PMID 37048534, 2023). "Although obesity due to leptin deficiency has been studied, most people with obesity do not have any abnormalities in the leptin gene." (PMID 38139229, 2023). "Estrogen level, sex-specific leptin resistance, and differences in gross locomotor activity may contribute to sex differences in obesity development." (PMID 37793910, 2023). "Moreover, the leptin-melanocortin pathway, related to obesity, has recently been proposed to be involved in depression." (PMID 37598204, 2023). "In obesity and MetS, the concentration of leptin increases, which is also a marker of inflammation." (PMID 37238721, 2023).